NRG1 (neuregulin 1)
Diseases named in the same sentence as NRG1 in open-access papers (continued):
Sharing a sentence is not in itself a finding about the gene and the disease.
myocardial infarction (24 papers, 2013 to 2025). Gross necrosis of the myocardium, as a result of interruption of the blood supply to the area, as in coronary thrombosis. "In animal experiments, NRG1 application improves various aspects of cardiac disease, including heart failure mortality, systolic and diastolic dysfunction, myocardial infarct size, and myocardial fibrosis." (PMID 39794341, 2025). "Some of these CpG sites annotated to genes previously implicated in cardiovascular diseases, including axonally derived neuregulin 1 (NRG1), known to play a role in myocardial repair following myocardial infarction." (PMID 40076974, 2025). "In CMs, NRG-1 activation reduced apoptosis after hypoxia-reoxygenation and intravenous NRG-1 administration reduced myocardial infarct size following IR." (PMID 33572486, 2021). "The exercise training is a way to activate NRG1/ErbB2 that has been able to improve the recovery and regeneration of cardiac muscle and reduce fibrosis in rats with heart attack." (PMID 32509881, 2020). "Some studies indicate that the activation of NRG1/ErbB2 can be an effective molecular strategy in the repair and regeneration of cardiac muscle after a heart attack." (PMID 32509881, 2020). "Significantly impaired systolic function was observed in NRG-1 knockout mouse model of myocardial infarction, which was significantly improved after NRG-1 intervention." (PMID 31317035, 2019). "It has been further demonstrated that exercise activates neuregulin-1/ErbB signaling and promotes cardiac repair after myocardial infarction in rats which shows its importance in cardiac regeneration in response to sports." (PMID 31547508, 2019). "We found that NRG-1 and IP had similar effects on reducing myocardial infarct size and apoptosis in vivo." (PMID 30134819, 2018). "NRG-1 induces hypertrophy and worsens cardiac performance in post-myocardial infarction (MI) rats." (PMID 37305740, 2023). "At the same time, exercise further up-regulated the activity of the NRG1/ErbB pathway and enhanced cardiac function, indicating that exercise may improve myocardial infarction in rats by activating the NRG1/ErbB pathway." (PMID 34526914, 2021). "Additionally, NRG1 has been used in clinical trials for the treatment of myocardial infarction in which increased cardio-protective effects were observed." (PMID 31396490, 2019). "In addition, controlled delivery of FGF1 and neuregulin-1 (NRG1) from biodegradable microparticles could promote cardiac repair in a rat myocardial infarction model through induction of tissue revascularization and activation of endogenous regeneration." (PMID 32210827, 2020). "Besides, endothelial derived NRG1 was shown to promotes ischemia-induced angiogenesis and arteriogenesis in the setting of hind limb ischemia which may explains the deleterious effect of endothelial specific KO of Nrg1 in the setting of myocardial infarction." (PMID 35874523, 2022). "Accordingly, a study found that reperfused myocardial infarction in rats was enhanced by the tissue-protective technique known as remote ischemic conditioning (RIC), which stimulates NRG-1 production in the infarcted tissue location." (PMID 36012430, 2022). "Activation of the tyrosine kinases ErbB2 and ErbB4 by neuregulin-1 in response to exercise activates PI3K/Akt signaling and protects ventricular myocytes against apoptosis as demonstrated in a myocardial infarction model in rats." (PMID 31547508, 2019). "NRG1, MSCs or MSC-ERBB4 (MSC with ERBB4 overexpression), were transplanted into mice following myocardial infarction." (PMID 25996292, 2015). "Some highly potent proteins in MSC-derived exosomes have the potential to improve cardiac function after myocardial infarction (MI), including growth factors such as fibroblast growth factor 1 (FGF1) and neuregulin-1 (NRG1), involved in cardiac development and regeneration in an MI rat model." (PMID 33396739, 2020).
Anxiety (23 papers, 2012 to 2025). Intense feelings of nervousness, tension, or panic often arise in response to interpersonal stresses. "Effects of Nrg1 mutation on locomotion, exploration and anxiety-like behaviors were age-dependent and interacted with the housing condition males were raised in." (PMID 23966917, 2013). "For example, Nrg1 mutation might enhance the responsiveness of targets of CBD suggested to be involved in modulating anxiety, such as the 5-HT1A receptor." (PMID 22509273, 2012). "NRG1 administration affected anxiety and hippocampal morphology independently to an obese-associated phenotype." (PMID 35220393, 2022). "We designed the experiments to verify the thesis that exogenous NRG1 protects against obesity-related neuroinflammation, anxiety, and altered morphology of the rat hippocampus." (PMID 35220393, 2022). "Further, Nrg1‐tg mice showed, increased anxiety, paralleled by higher frequency of defecation and urination during the open‐field test (Fig EV5E–G), supporting previous observations." (PMID 28743784, 2017). "Further, complex gender specific interactions of type II Nrg1 genotype and adolescent chronic variable stress were reported on anxiety-related behavior and cued fear conditioning." (PMID 25324742, 2014). "Surprisingly, older Nrg1 mutants appeared insensitive to anxiety-like-related stress effects in the open field (i.e., center locomotion)." (PMID 23966917, 2013). "Nrg1 mutants kept in ME developed hyper-exploration in the light-dark test and reduced anxiety-like behavior in the open field test at 3–4 months of age whereas Nrg1 males kept in standard housing displayed these phenotypes only at the age of 4–6 months." (PMID 23966917, 2013). "Conversely, only WT mice developed tolerance to cannabinoid-induced anxiety and Nrg1 HET mice maintained a persistent anxiogenic response to repeated cannabinoid exposure." (PMID 23447498, 2013). "The fact that anxiolytic-like effects of CBD were only observed in the OF test reflects the importance of the choice of anxiety test used to explore the effects of pharmacological and genetic manipulations in Nrg1 TM HET and CBD-treated C57BL/6JArc mice." (PMID 22509273, 2012). "Vehicle-treated Nrg1 TM HET mice showed reduced anxiety-like behaviour on test day 1 in the LD test and on the last test day in the OF paradigm." (PMID 22509273, 2012). "Nrg1 appears necessary for CBD-induced anxiolysis since only WT mice developed decreased anxiety-related behaviour with repeated CBD treatment." (PMID 22509273, 2012). "In this study, we hypothesized that NRG1 administration would confer protection against the detrimental effects of an obesogenic diet on neuroinflammation, hippocampal maturation, and anxiety-like behaviors." (PMID 35220393, 2022). "Moreover, administration of exogenous NRG1 reduces anxiety-like behaviors and increases GABAergic transmission in mice." (PMID 27192432, 2016). "In addition, disturbing neuregulin-1-ErbB4 signaling in OLs can also lead to increased dopamine receptors and transporters and anxiety-like behaviors in mice." (PMID 26696827, 2015). "It should be noted that a series of control experiments regarding normal profiles of basic behavioral phenotypes was reported previously in Akt1+/− or Akt1−/– mice and in Nrg1+/− mice, such as locomotor activity, anxiety-like behavior, olfactory function, and sensorimotor gating function." (PMID 25688191, 2014). "We reasoned that examining the responses of the hippocampal NRG1-ErbB4 system to obesogenic diets during adolescence may provide valuable insights into the potential contribution of this pathway to obesity-induced hippocampal deficits and anxiety." (PMID 35220393, 2022). "Likewise, the expression of Erbb4 is increased in CCK-SAP rats compared with control rats: mice with high anxiety phenotype display low levels of ErbB4 in the amygdala, and administration of its ligand neuregulin 1 is anxiolytic while enhancing GABAergic neurotransmission." (PMID 35965105, 2022).
Anxiety (continued). "Thus, it possible that increased BACE1-mediated processing of NRG1 could lead to increased GABAergic transmission and reduced anxiety." (PMID 27192432, 2016). "For example, Nrg1 heterozygous knockout mice with TMc-domain truncation of exon 11 were first reported in 2002 and this original TMc-Nrg1+/− mutant strain has been reported to exhibit behavioral deficits in locomotor activity, explorative behavior, and anxiety-like behaviors." (PMID 24782733, 2014). "Conversely, wild-type mice (but not Nrg1 HET) mice developed tolerance to cannabinoid-induced anxiety, whereas Nrg1 HET mice showed a persistent anxiogenic response to chronic cannabinoid exposure." (PMID 25426017, 2014). "The phenomenon of a disconnected behavioral and endocrine stress response of older Nrg1 mice (i.e., no stress-induced anxiety-like response in open field but increased glucocorticoid levels) is consistent with other mouse models." (PMID 23966917, 2013). "While anxiety was not assessed in adult mice neonatally overexposed to NRG1, peripheral exposure to NRG1 in adult mice induces an anxiolytic phenotype, therefore, it is possible that NRG3 may also have temporally regulated effects." (PMID 25093331, 2014). "No pronounced effect of Nrg1 on the endocrine and behavioral effects of acute restraint stress—only subtle, age-dependent modification of stress-induced corticosterone release and anxiety-like behaviors." (PMID 23966917, 2013). "On the other hand, the anxiolytic effect of long-term CBD (1 and 100 mg/kg) in the OF in WT mice was not present in Nrg1 TM HET mice, suggesting that the effects of CBD on anxiety-related behaviour are dependent on an intact Nrg1 transmembrane domain." (PMID 22509273, 2012). "Nrg1 genotype also modulated tolerance to the effects of cannabinoids, with Nrg1 HET mice developing tolerance more rapidly to locomotor suppression and hypothermia than WT mice, but conversely showing a lack of tolerance to cannabinoid-induced anxiety unlike WT mice." (PMID 23447498, 2013).
non-small cell lung carcinoma (23 papers, 2015 to 2026). A group of at least three distinct histological types of lung cancer, including non-small cell squamous cell carcinoma, adenocarcinoma, and large cell carcinoma. "Adding GRP to non-small cell lung cancer (NSCLC) cells causes the secretion of NRG1, which activates HER4." (PMID 41007372, 2025). "Detection of NRG1 and NTRK fusions was most improved due to the challenges of baiting these genes on DNA-NGS with 67% of NRG1 RE+ non-small cell lung cancer (NSCLC) and 67% of NTRK RE+ solid tumors identified on RNA alone." (PMID 41512295, 2026). "The US Food and Drug Administration granted accelerated approval to a HER2/HER3 antibody, zenocutuzumab, for treatment of NRG1 fusion-positive non-small cell lung cancer and pancreatic ductal adenocarcinoma (PDAC)." (PMID 41390931, 2026). "Zenocutuzumab is an antibody indicated to treat adult patients with advanced unresectable or metastatic non-small cell lung cancer (NSCLC) harboring a neuregulin 1 (NRG1) gene fusion with disease progression on or after prior systemic therapy." (PMID 40868216, 2025). "This is the first targeted drug approved by the FDA for the treatment of patients with NRG1 fusion-carrying non-small cell lung cancer or pancreatic cancer." (PMID 40730881, 2025). "For example, zenocutuzumab, a bispecific HER2xHER3 antibody, has been approved by the U.S. Food and Drug Administration (FDA) for the treatment of Neuregulin 1-positive (NRG1+) non-small cell lung cancer and pancreatic ductal adenocarcinoma." (PMID 40881578, 2025). "For example, NRG1 fusions with CD74 are predominantly seen in non-small cell lung cancers (NSCLCs), the NOTCH2-NRG1 fusion in gallbladders cancers, and the CDH1-NRG1 fusion in pancreatic ductal adenocarcinoma." (PMID 38369520, 2024). "NRG1 fusions are rare oncogenic drivers in solid tumors, and the incidence of NRG1 fusions in non-small cell lung cancer (NSCLC) was 0.26%." (PMID 37587479, 2023). "For instance, zenocutuzumab, a bsAb against HER2 and HER3, potently inhibits heregulin (HRG)-driven signaling of HER2-HER3 heterodimerization and has received accelerated FDA approval for patients with NRG1 fusion-positive non-small cell lung cancer (NSCLC) or pancreatic adenocarcinoma." (PMID 41221272, 2025). "The RAIN-701 trial is a preclinical model in which tarloxotinib was evaluated in patients with advanced non-small cell lung cancer (NSCLC) harboring EGFR Exon 20 insertions or HER2 activating mutations, as well as those with NRG1, EGFR, HER2, or HER4 gene fusions." (PMID 40710312, 2025). "Sun and colleagues found that both NRG1 and NRG2 functioned as ligands of ERBB family and involved in progression of non-small cell lung cancer." (PMID 30123134, 2018). "In 12 non-small cell lung-cancer (NSCLC)-cell line, 75% had HER4 mRNA expression, with NCI-H522 and NCI-H661-cells having the highest levels of GRPR, HER4, and the HER4-ligand neuregulin (NRG1)." (PMID 41007372, 2025). "In addition to significant benefit in treatment-naïve non-small cell lung cancer (NSCLC) with non-resistant EGFR mutations, afatinib has shown notable efficacy in tumors, including PDA, harboring neuregulin (NRG1) fusions, as seen in the basket study TAPUR." (PMID 40507311, 2025). "ERBB3/ERBB4 heterodimers may also be active and relevant for disease relapse in non-small cell lung cancer, where inhibition of ligand-dependent ERBB3/ERBB4 signaling with a NRG1-blocking antibody enhanced the magnitude and duration of response to chemotherapy in various mouse models." (PMID 26745281, 2016).
melanoma (22 papers, 2005 to 2025). A malignant, usually aggressive tumor composed of atypical, neoplastic melanocytes. "In order to assess in greater detail this aspect we conducted the present study in a panel of V600 BRAF-mutated human melanoma cell lines and utilizing a combination of approaches involving the use of conditioned medium from BRAFi exposed cells and of neutralizing antibodies against NRG1." (PMID 31557826, 2019). "As in thyroid cancers, NRG1-induced HER3 activation plays an important role in adaptive resistance to RAF or MEK inhibitors in melanomas, whereas EGFR plays a more critical role in colorectal cancers." (PMID 36476495, 2022). "In human melanocytes, MAPK signaling causes reduction of MITF and increases ERBB3, FOXD3 and NRG1 transcription factor gene expression, with NRG1 and FOXD3 also further upregulating ERBB3, which can heterodimerize with EGFR causing melanoma metastasis." (PMID 34067095, 2021). "Under the influence of CM derived from NRG1-depleted fibroblasts, melanoma cells exhibited an increase in ERBB3 signaling at a much lower level compared to the control." (PMID 33430277, 2021). "The NRG1 level in melanoma cells was very low or undetectable, whereas in normal and cancer-associated fibroblasts it was relatively high." (PMID 33430277, 2021). "FOXD3 is then able to directly activate the expression of ERBB3 at the transcriptional level, enhancing the responsiveness of melanoma cells to NRG1 (the ligand for ERBB3), and thus leading to the reactivation of both MAPK and PI3K/AKT pathways." (PMID 33507915, 2021). "Our data suggest that also melanomas activate the ErbB3 receptor soon after exposure to MAPK inhibitors probably through NRG1 overexpression in order to counteract the anti-proliferative effect of targeted therapy." (PMID 31557826, 2019). "While these data underscore the strong degree of heterogeneity of melanoma cell lines, they confirm that one of the prominent and constant adaptive response is the upregulation of NRG-1 expression." (PMID 31557826, 2019). "The ERBB2-ERBB3 heterocomplex induced by NRG1 is emerging as important for growth of non-small cell lung, breast, and melanoma cell growth." (PMID 27626312, 2016). "First of all we compared the proliferative response of MST-L melanoma cells pre-treated with each mAb alone or their combination and then incubated with NRG1 (HRG) for 48, 72 and 96 h in the presence of the mAbs." (PMID 26208478, 2015). "In NHEK cells, for example the down-regulated mitogens neuregulin 1 (heregulin) and melanoma growth stimulatory activity (MGSA), belong to this group." (PMID 16001974, 2005). "It has also been suggested that neuregulin 1 (NRG1)/HER3 signaling may contribute to melanoma progression and metastasis." (PMID 36765036, 2023). "Neuregulin 1 (NRG1) is another paracrine factor through which CAFs may influence melanoma response to MAPK inhibitors." (PMID 33036192, 2020). "Interestingly, previous work in melanoma has shown that stimulation of the Notch receptor leads to upregulation of NRG1, and thus it is possible that a positive feedback loop is being activated." (PMID 29636067, 2018). "NRG-1 in melanoma cell media was assessed using Bio-Plex Pro NRG-1 Assays (Bio-Rad)." (PMID 27461275, 2016). "NRG1, highly expressed in fibroblasts and CAF, is a ligand for ErbB3, and fibroblast-derived NRG1 can attenuate the effect of RAF inhibitors on melanoma cells." (PMID 37784082, 2023). "Further studies are necessary to explore the biological significance of NRG1 deletion in RMM patients and how this affects the progression of melanoma." (PMID 34044811, 2021). "Based on previous results we decided to focus our attention on two melanoma cell lines, namely WM266 and WM115, which show early and intermediate times of NRG-1 up-regulation upon BRAF inhibition respectively." (PMID 31557826, 2019).